INS (insulin)
Diseases named in the same sentence as INS in open-access papers (continued):
Sharing a sentence is not in itself a finding about the gene and the disease.
diabetes (continued). "Consuming a combination of GTC and CCA for three weeks significantly improved postprandial glycemic control, GLP-1 response, and postprandial insulin sensitivity in healthy individuals and may be effective in preventing diabetes." (PMID 36501092, 2022). "Some healthcare providers failed to take ownership of the intervention because they believed that it was not their duty to complete the prescribed tasks, even though initiating patients on insulin is their responsibility according to the guidelines for the management of diabetes in primary care." (PMID 35924623, 2022). "Patients with diabetes receiving insulin treatment are likely to require more frequent clinical visits with endocrinologists in addition to primary care physicians and are likely to require more prescription refills for diabetes management." (PMID 35019844, 2022). "Therefore, reduced responsiveness of skeletal muscle to insulin, known as insulin resistance, is an important aspect in the development of type 2 diabetes mellitus (T2DM)." (PMID 36678522, 2022). "From these initial landmark reports, it was apparent that the diabetes phenotype linked to mitochondrial dysfunction was variable and spanned insulin dependence through to non-insulin-dependent diabetes." (PMID 35552684, 2022). "Limited staff for diabetes education, low patient education, patient refusal, exaggerated fears of insulin side effects, and inadequate consultation time were the main barriers to insulin acceptance and prescription." (PMID 36554673, 2022). "A recent analysis showed that PC risk associated with insulin therapy is dependent not on the type of hypoglycaemic drug as on the diabetes subtype." (PMID 35893093, 2022). "The main factors associated with negative outcomes are male gender, urban residence (there could be a bias regarding accessibility), long duration of diabetes mellitus, and insulin-dependency status." (PMID 36013336, 2022). "The differences between the results in our study population could be due to long-standing diabetes or long-term insulin treatment." (PMID 35454146, 2022). "However, paralysis appears to promote a phenotype prone for hyper-secretion of insulin at rest and after ingestion of carbohydrates, which likely leads to insulin resistance and diabetes." (PMID 36278750, 2022). "The management of diabetes disease using insulin injection for a longer period is maybe inconvenient and psychologically stressful." (PMID 36419111, 2022). "Thus, inactivation of Haster in the germline or in the pancreas led to impaired insulin secretion and diabetes." (PMID 36202974, 2022). "Trehalose, just as some rare carbohydrates (isomaltulose and d-tagatose) do, regulates glucose metabolism and supports glucose homeostasis in patients with diabetes but can also improve insulin sensitivity, subsequently leading to better control of hyperglycemia." (PMID 35330193, 2022). "Insulin is used to treat type 1 diabetes mellitus and type 2 diabetes mellitus." (PMID 36358909, 2022). "However, oral disposition index was significantly higher in the Diabetes-β-Cell-Failure group compared to the Diabetes-Insulin-Resistance group (P = 0.002)." (PMID 36211668, 2022). "Data from the MEDIM study has revealed that Iraqi migrants in Malmö are at twice the risk of T2D and have younger age of disease onset compared with the Swedish born population, with high burden of diabetes family history, and poorer glycemic control and insulin sensitivity." (PMID 35227251, 2022). "Of all diabetes patients, 85.9% used oral antidiabetics (alone or in combinations), 49.5% used insulin alone or in combinations, and 29.3% used both oral antidiabetics and insulin." (PMID 35653361, 2022). "In a similar study, Sprague-Dawley rats with streptozotocin-induced diabetes treated with 10 mg/kg body-weight/day ZnO NPs for 30 days resulted in more normalized blood glucose and insulin levels, as well as increasing the GLUT2 and glucokinase expression in the liver tissue." (PMID 35887304, 2022).
diabetes (continued). "Diabetes is a heterogeneous group of metabolic disorders, defined by persistent hyperglycemia due to both defects in insulin secretion and action, culminating in abnormal glucose metabolism with lifelong micro- and macro-vascular complications that develop from chronic hyperglycemia." (PMID 36361703, 2022). "In addition, miR-192 suppresses Glucagon-like peptide-1 expression as a strong insulin secretagogue, thereby further promoting type 1 diabetes mellitus." (PMID 35655590, 2022). "Nanotechnology in diabetes research has played several roles in improving the outcome of diabetic management in diabetics through the deployment of novel nanotechnology-based glucose measurement and insulin delivery techniques." (PMID 36289697, 2022). "Patients with albuminuria had higher systolic blood pressure, a longer duration of diabetes, higher A1C levels, higher triglyceride levels, and a higher prevalence of use of insulin and angiotensin converting enzyme inhibitors (ACEi)/angiotensin II receptor blockers (ARB)." (PMID 36175599, 2022). "However, overall, the study also stated that diabetes mellitus was associated with a higher risk of DIC, particularly when it had been treated recently with insulin." (PMID 36060388, 2022). "Additionally, it has been shown that water-soluble alcoholic extracts of G. sylvestre leaves enhance insulin release from pancreatic B cells in various animal models of hyperglycemia and diabetes." (PMID 35268815, 2022). "As intra-islet blood vessel is important for glucose sensing and insulin distribution, whether endothelia-specific endoglin would play a role in islet function in stressed conditions, such as diabetes, could be an interesting issue." (PMID 35327565, 2022). "Also designated mutant INS-gene induced diabetes of the young (MIDY), MPS encompasses a range of patient phenotypes, representing subtypes of permanent neonatal diabetes mellitus (PNDM) to maturity-onset diabetes of the young (MODY)." (PMID 35299958, 2022). "Treatment of the STZ mice with insulin attenuated the diabetes-mediated repression of Vdbp expression, which may indicate a role for the insulin signaling in the regulation of Vdbp expression." (PMID 35524739, 2022). "Similarly to healthy cells in the course of diabetes and insulin resistance, EC cells are affected by disruptions in the insulin and IGF-1 receptor pathways involved in the growth of tumour cells." (PMID 35743146, 2022). "Vitamin K is a good treatment for patients with diabetes because of the release of insulin." (PMID 36079754, 2022). "Autoimmunity resulted as a non-leading cause of post-therapy diabetes, since the presence of no more than one positive pancreatic autoantibody was registered, in the face of several glucose and insulin imbalances." (PMID 36551851, 2022). "While some of these women may have had diabetes and may have switched to insulin, others might have used it to treat polycystic ovary syndrome and discontinued it once they were pregnant." (PMID 35162474, 2022). "Also, antagonizing the glucagon receptors has shown to be effective in improving insulin sensitivity in models of diabetes and obesity." (PMID 35931683, 2022). "This type of diabetes can only be treated with insulin therapy." (PMID 36072265, 2022). "Moreover, SIRT2 regulates cellular energetic state by modulating the action of insulin and the lipogenesis, hence it is regarded as a promising target in obesity, liver steatosis, and diabetes." (PMID 35409409, 2022). "Limited data from human-based studies reveal that resveratrol improves insulin sensitivity and fasting glucose levels in patients with Type 2 Diabetes Mellitus and may improve inflammatory status in human obesity." (PMID 35889827, 2022). "Understanding early uptake of insulin biosimilars in NHs, where diabetes and insulin use are prevalent, may help to anticipate the trajectory of use in other clinical settings in the US while also providing due attention to a vulnerable population." (PMID 35600866, 2022).
diabetes (continued). "It is not surprising that current peptide therapeutics for neurological disorders target alternative, well-characterized systems and mechanisms, the majority of which focus on peripheral symptoms, including those in the treatment of diabetes mellitus with insulin or GLP-1." (PMID 35203552, 2022). "These medications, including insulin, exist to control and maintain glucose or sugar levels in the blood and thus more commonly used to manage diabetes, adversely affect bone metabolism, especially by impairing osteoblast function and activating osteoclastogenesis." (PMID 35453723, 2022). "Moreover, it has been shown that adding metformin to insulin therapy to patients with type 1 diabetes mellitus (T1DM) resulted in greater glycemic control and a greater decrease in HbA1c." (PMID 35267644, 2022). "However, children and adolescents with diabetes are yet to benefit from these advances with primary diabetes treatments in children being limited to metformin and insulin." (PMID 34913986, 2022). "Thus, we next measured expression of Pgc-1α and a GR target gene tyrosine aminotransferase (Tat) to analyze activation status of these regulatory pathways in response to the STZ-induced diabetes and the potential effect of insulin therapy." (PMID 35524739, 2022). "The diagnosis of diabetes occurs when the human body is not able to produce adequate insulin or when cells fail to respond effectively to insulin, causing systemic dysregulation of blood glucose levels." (PMID 35600597, 2022). "Phytonutrients, or natural compounds found in plants, may have anti-obesity and anti-diabetes effects by modulating physiological pathways that regulate appetite, metabolism, and insulin sensitivity." (PMID 36145160, 2022). "Chronic High fat diet insulin resistant to exposure results in liver damage,impaired glucose homeostasis, hyperinsulinemia, late pancreatic-cell failure to generate insulin due to cell exhaustion, and subsequent hyperglycaemia, all of which are hallmarks of Type 2 Diabetes Mellitus (T2DM)." (PMID 35815199, 2022). "Dated studies in patients with MRDM and BMI < 18 kg/m2, reported fasting C-peptide levels intermediate between those of T1D and T2D subjects, and both basal and stimulated insulin plasma levels consistently lower than obese with diabetes, though enough to avoid ketosis." (PMID 36614099, 2022). "Nevertheless, a common denominator across virtually all classifications of diabetes is the failure of sufficient insulin secretion from β cells, whether due to reduced β cell mass or β cell dysfunction." (PMID 35817393, 2022). "In addition, some patients received new medications for diabetes, such as insulin, sulfonylureas and acarbose, while the number of patients on metformin remained unchanged." (PMID 34585841, 2022). "These diabetes policies must be attentive to factors affecting access to medicines for diabetes patients because the key to effective diabetes management includes adherence to insulin and oral medicines." (PMID 36962297, 2022). "This tissue accounts for more than 80% of insulin-stimulated glucose uptake and has a major impact on whole-body metabolic homeostasis, and it is the main factor for diabetes mellitus development, suggesting that it could be relevant for the aging process." (PMID 35453736, 2022). "Similar to the UK population, non-insulin treatment, a parent with diabetes, HbA1c ≤ 58 mmol/mol (7.5%) and a composite clinical probability of MODY ≥10% were useful in identifying autosomal dominant diabetes in the Turkish cohort (OR 105.1, 6.2, 10.3 and 38, respectively, all p ≤ 0.0003)." (PMID 34686905, 2022). "Therefore, differentiating between the different types of diabetes is crucial for deciding therapeutic strategies for optimal management, and the measurement of endogenous insulin secretion has been shown to be helpful." (PMID 35462815, 2022).
diabetes (continued). "Besides, hepatitis C virus can affect insulin signaling, influence lipid metabolism, and damage islet cells, thus contributing to the development of diabetes; HIF-α is closely related to the development of diabetes and its complications." (PMID 35656465, 2022). "In diabetes-induced rabbit and mouse models, preimplantation embryos exposed to hyperglycemia resulted in perturbed insulin-mediated glucose metabolism, decreased glucose transport and utilization, reduced developmental competence and cell numbers, and increased apoptosis in the ICM." (PMID 36497026, 2022). "More than 90% of all diabetics have T2D, which is characterized by a decrease in the number of β cells or a decline of β cells function, resulting in an inability to compensate for the high insulin requirement in insulin resistant states." (PMID 36302749, 2022). "As the antilymphocyte adaptive agent, azathioprine and prednisone could induce immunosuppression and reduce insulin requirements at the onset of diabetes." (PMID 36405706, 2022). "The exact cause of diabetes is unknown, but some studies have shown that diabetes (type I) in children is the result of the immune system destroying the insulin-producing cells (beta cells) in the pancreas by mistake." (PMID 36188660, 2022). "In low-insulin states such as diabetes, leptin is decreased and increases after insulin treatment." (PMID 35386146, 2022). "A first-of-its-kind smart pen cap for insulin pens (Bigfoot UnityTM Diabetes Management System) launched by Bigfoot Biomedical received FDA clearance in May 2021." (PMID 35355552, 2022). "Moreover, this study will provide important information regarding the safety of intermittent fasting in people with type 2 diabetes mellitus using basal bolus insulin treatment and guidance on how the insulin dose should be adjusted in this population." (PMID 35179802, 2022). "The great interest in insulin determination, therefore, results in the preparation of voltammetric assays for its sensitive measurement in human serum and plasma samples and in injections commonly used by people with diabetes." (PMID 36557132, 2022). "Odds ratio of insulin (vs diet only or non-insulin hypoglycemic agents) for each diabetes subgroup." (PMID 36457559, 2022). "We concluded that some pancreatic acinar and ductal cells could act as a functional reserve of insulin production in the case of islet β-cells dysfunction in experimental diabetes." (PMID 35457103, 2022). "At baseline, 71% took oral diabetes medication and 24% used insulin." (PMID 36231282, 2022). "Therefore, imeglimin exerts protective effects against insulin resistance as well as insufficient insulin secretion both of which are main characteristics of type 2 diabetes mellitus." (PMID 35918386, 2022). "Retinoic acid can improve the symptoms of diabetes in mice by promoting insulin secretion." (PMID 36235858, 2022). "Yet, whether insulin itself exerts any profibrotic effects on the left ventricle in diabetes remains unknown." (PMID 35574440, 2022). "Interestingly, pathway enrichment analyses of hub proteins conducted in GeneTrail revealed that these genes are involved in insulin signaling, mature onset of diabetes, insulin resistance, inositol phosphate metabolism or AMPK signaling pathway." (PMID 36451736, 2022). "Of the 91 subjects with known diabetes, the mean duration of diabetes was 6.5 ± 5.4 years, and 50.5% were treated by oral hypoglycemic drugs, 13.2% by insulin alone or in combination with oral drugs, 19.8% by lifestyle measures only and the rest unclassified due to missing data." (PMID 36079764, 2022). "Type 2 diabetes mellitus (T2DM) is a group of MetS that is characterized by absolute or relative insufficiency of insulin secretion, and decreased sensitivity of target organs to insulin, followed by metabolic disorders of fat, protein, water, and electrolytes." (PMID 36355500, 2022).
diabetes (continued). "Amylin (IAPP), a gluco-modulatory hormone co-expressed with insulin by pancreatic β cells, is downregulated in both T1D and advanced T2D, while amylin agonists are considered novel therapeutic agents for treating diabetes." (PMID 35788821, 2022). "Insulin therapy was initiated in 28% of the participants at the time of diagnosis of diabetes." (PMID 36109715, 2022). "GWAS investigating genetic determinants of insulin concentrations in individuals without diabetes highlighted that many identified loci showed associations with markers suggestive of clinical IR, such as high triglyceride and low HDL concentrations." (PMID 35456983, 2022). "It was previously suggested that inhibition of IDE may improve insulin activity in a diabetes mouse model." (PMID 35350789, 2022). "Seeing graphic representations of activity data rather than relying on patient recall may help CDCES’ and the care team to make more informed decisions around insulin dose adjustments and overall diabetes care." (PMID 36714600, 2022). "These substances have shown a beneficial effect concerning diabetes mellitus, acting in several ways, such as regulating glucose biochemical pathways, glucose tolerance, lipid profile, glycogen biosynthesis, glucose uptake, and insulin release." (PMID 37746194, 2022). "It is suggested that although FGF-19 and FGF-21 are activated under different conditions, they show a similar function in their controlling of glucose and insulin metabolism, energy and weight balance as well as lipid concentrations, particularly in metabolic disorders such as obesity or diabetes." (PMID 36362225, 2022). "The recommendations indicate the necessity of using modern ultrafast acting insulin analogs, new diabetes technologies, namely insulin pumps with low glucose suspension function, and continuous glucose monitoring systems to improve metabolic control and reduce glucose variability." (PMID 36012972, 2022). "Compared to matched controls, women after IUFD had a greater BMI (p = 0.002), were more often smokers (p<0.001), and suffered more frequently medical conditions, such as hypertension (p = 0.015), APS (p = 0.017), and diabetes (p<0.001), with a more frequent need for insulin (p = 0.006)." (PMID 35051188, 2022). "Moreover, reports have increasingly demonstrated that a functioning pancreas transplant not only makes the patient insulin-independent and normoglycemic but also protects both the kidney and other target structures from chronic complications of diabetes." (PMID 35329847, 2022). "Additionally, it is known that common genetic variations of TCF7L2 are associated with type 2 diabetes mellitus and that subjects with its high-risk allele of TCF7L2 show impaired insulin secretion." (PMID 35453568, 2022). "This responsiveness to insulin combined with a fetal overexposure induced by maternal obesity or diabetes may result in fetal cardiac cell overgrowth." (PMID 35258482, 2022). "Insulin users were older (56.7± 13.1 vs. 50.6 ± 12.9 years; p < 0.001), had longer diabetes duration (12.1 ± 7.1 vs. 8.7 ± 6.5 years; p < 0.001), and had higher HbA1C (9.50 ± 1.70 vs. 8.84 ± 1.60 %; p < 0.001), whereas body mass index (BMI) was lower (29.4 ± 5.2 vs. 31.3 ± 5.3; p = 0.001)." (PMID 36559020, 2022). "Patients in the intervention group were instructed to use a smartphone application that allows users to enter data regarding diabetes self-management, such as diet, physical activity, blood glucose, insulin doses and other medications in addition to usual care (face-to-face visit every 3 months)." (PMID 36141289, 2022). "The main objective was to address the barriers toward insulin initiation and intensification among primary care physicians (PCPs) so as to start tackling these barriers and improve quality of care and decrease the burden of diabetes-related complications." (PMID 36554673, 2022). "Mice with impaired signal transduction show impaired insulin secretion, leading to diabetes." (PMID 36700071, 2022).